TFEB (transcription factor EB)
Diseases named in the same sentence as TFEB in open-access papers (continued):
Sharing a sentence is not in itself a finding about the gene and the disease.
cancer (continued). "The MiT/TFE family of transcription factors (MITF, TFE3, and TFEB), which control transcriptional programs for autophagy and lysosome biogenesis have emerged as regulators of energy metabolism in cancer." (PMID 32397616, 2020). "Altogether, these results unveil the role of TFEB as a pro-survival factor in cancer cells through the upregulation of p21." (PMID 32397616, 2020). "The levels of TFEB and TFE3 are elevated in multiple types of human cancers and have been linked with both occurrence and poor prognosis." (PMID 33145941, 2020). "The expression of the TFEB and TFE3 and their activity are elevated in multiple types of human cancers and associated with enhanced proliferation and motility of these cancer cells." (PMID 33145941, 2020). "We further study the role of the TFEB-p21 pathway in cancer cell survival by testing the efficacy of doxorubicin to promote caspase-3 cleavage at two different concentrations." (PMID 32397616, 2020). "At the transcription level, despite of being unexclusive, previous reports have shown that multiple transcription factors such as HIF1α, STAT3, SREBP, and TFEB can be closely regulated by mTORC1 in cancers." (PMID 32234750, 2020). "We found that TFEB depletion dramatically downregulates the basal expression of p21 protein in both normal and cancer cell types." (PMID 32397616, 2020). "To evaluate this idea, we ectopically expressed the wild-type and S463D mutant of TFEB in three human cancer cell lines to modulate lysosomal acidification/activation and treated the cells with EGFR inhibitors under hypoxia." (PMID 31717697, 2019). "In this study, we demonstrated that TFEB plays a pivotal role in acquisition of nutrients required for growth in KRAS-mutant cancer cells under nutrient-depleted conditions." (PMID 30400219, 2018). "Very recently, enhancement of TFEB expression and activity has been shown in several cancer cells where it helps to increase tumor growth and malignancy through enhancing cancer cell autophagy and upregulating the endosomal-lysosomal compartment." (PMID 30360758, 2018). "Amino acid limitation that inactivates mTORC1 promotes de-phosphorylation and nuclear translocation of Transcription Factor EB (TFEB), a key transcriptional regulator of lysosome biogenesis and autophagy that is deregulated in cancer and neurodegeneration." (PMID 29992949, 2018). "Accordingly, TFEB can compensate for nutrient shortage by promoting generation of metabolic intermediates required for cancer growth under nutrient-depleted conditions." (PMID 30400219, 2018). "As TFEB is a central player in cancer, our approach to time series analyses of magnitude and dynamics of subpopulation shifts enables biomarker assessment of cell line sensitivity and responsiveness." (PMID 27268034, 2016). "Several studies showed potential involvement of TFEB in cancer, although that appears to be related to the cancer type." (PMID 27992857, 2016). "Translocation-induced overexpression of TFE3 or TFEB fusion proteins is important in proliferation, anchorage independent growth, migration and long term survival of cancer cells." (PMID 21209915, 2010). "We have shown that 2-DG activates a TFEB-UPR axis while suppressing cancer stemness." (PMID 39814550, 2025). "Activation of TFEB has been reported to be involved in the regulation of several cancers." (PMID 40779629, 2025). "Aside from lysosomal biogenesis and autophagy, TFEB has been studied in the context of angiogenesis, immune response, epithelial–mesenchymal transition, and cancer metabolism, among other processes in various disease-related models." (PMID 39814550, 2025). "We next wondered whether the role of TFEB was conserved in mammalian diapause models, including mouse embryonic diapause and human cancer dormancy." (PMID 40588651, 2025). "In both worm and mammalian cancer diapause models, TFEB and TGFβ components are highly regulated." (PMID 40588651, 2025).
cancer (continued). "Having found evidence for a conserved role of TFEB in mammalian embryonic diapause, we asked if its function could be extended to the recently reported human cancer cell diapause-like state." (PMID 40588651, 2025). "While TFEB transcriptional activity is typically monitored by qPCR analysis of its target genes, also DIA‐LC‐MS/MS was utilized to characterize changes in TFEB‐induced lysosomal protein expression levels between WT and phosphorylation‐resistant TFEB versions in a cancer cell model." (PMID 41097905, 2025). "Zhitomirsky and Assaraf demonstrated that nanomolar doses of weakly basic drugs stimulate cancer cells to increase lysosome numbers through Transcription Factor EB (TFEB)-mediated biogenesis, effectively expanding the lysosomal “sink” and compounding multidrug resistance (MDR) over time." (PMID 41373734, 2025). "The loss or inhibition of TRPMLs reduces, eg, cancer cell migration and invasion, and roles of TRPMLs in TFEB-mediated gene transcription and lysosomal exocytosis promoting invasiveness and drug resistance in cancer cells, cancer cell nutrient sensing, and antitumor immunity have been proposed." (PMID 41118703, 2025). "We highlighted earlier that TFEB promotes cancer stemness in TNBC." (PMID 39814550, 2025). "LONP1 inhibitor CDDO has shown promising anti-cancer activity and it is compelling to speculate that the outcome could be influenced by the mitochondrial function of TFEB." (PMID 38263327, 2024). "Safe and effective strategies for activating TFEB might be considered as a therapeutic approach for cancer and neurodegenerative disease treatment and for extending longevity." (PMID 38612708, 2024). "Thus, when there is an energy demand, TFEB is activated and promotes autophagy to provide an additional energy supply to cancer cells, which promotes cancer cell survival and cancer progression; thus, it is considered an oncogenic gene." (PMID 38938061, 2024). "TFEB was found to be highly expressed relative to paraneoplastics in various cancer cell lines." (PMID 38938061, 2024). "TFEB is upregulated in prostate cancer and is thought to promote cancer progression by regulating lysosome biogenesis and plays a role in the resistance of cancer cells to the taxane docetaxel." (PMID 39796673, 2024). "Moreover, it has been shown that TFEB overexpression as well as a positive feedback mechanism between mTORC1 and TFEB was sufficient to promote cancer growth in mouse models." (PMID 36709383, 2023). "In addition, in response to nutrient deprivation, cancer cells use TFEB to promote their own survival." (PMID 37243374, 2023). "According to its involvement in autophagy flux control, TFEB may participate in many regulatory pathways of energy production and biosynthesis; in fact, it has been reported to regulate energy metabolism in cancer." (PMID 37160873, 2023). "Emerging evidence has shown the contribution of TFEB in the development of cancers." (PMID 35625599, 2022). "Interestingly, a well-established histone deacetylase inhibitor, suberoylanilide hydroxamic acid, can activate lysosomal function in human cancer cells by enhancing TFEB acetylation at K91, K103, K116, and K430." (PMID 35625599, 2022). "Cells rely on effective lysosomal function, and increasing evidence indicates that cancer cells may utilize TFEB-dependent transcriptional activation of lysosomal degradation pathways to maintain survival." (PMID 35970822, 2022). "So far, TFEB agonist, such as rapamycin, has been approved for the treatment of cancer." (PMID 33562649, 2021). "TFEB transcription activity is enhanced with histone deacetylase inhibitor suberoylanilide hydroxamic acid, which results in the activation of lysosomal function in human cancer cells." (PMID 33562649, 2021). "Finally, we found that in various types of cancer, the levels of TFEB mediated Wnt target genes exhibit strong correlations with the level of Axin2, which represents the activity of Wnt signaling." (PMID 33753903, 2021).
cancer (continued). "In contrast, in cancer cell lines, inhibitors of histone deacetylases indirectly favor acetylation of Lys 91, 103, 116, and 430 at the nuclear level and increase TFEB transcriptional activity." (PMID 33912071, 2021). "Overall, these data imply that TFEB mediates Wnt signaling for cancer progression." (PMID 33753903, 2021). "Consequently, in our study we demonstrated that TFEB overexpression induced lysosome synthesis and promoted cancer cell proliferation, invasion, and migration in PCa." (PMID 33732651, 2021). "Moreover, in pancreatic cancer, TFEB-induced autophagic activation leads to cancer progression via increased migration and metastasis of cancer cells due to endocytosis of Itgα5 and disassembly of adhesion machinery." (PMID 33912071, 2021). "In short, cancer cells benefit by mai17ntaining dephosphorylated TFEB levels." (PMID 34572262, 2021). "Transcription factor EB (TFEB) represents an emerging player in cancer biology." (PMID 33252196, 2020). "Collectively, the uncovered TFEB-p21 pathway may represent a new target for therapeutic intervention in different kinds of cancers." (PMID 32397616, 2020). "Then, we asked whether the modulation of TFEB protein levels could be relevant modulating the cell cycle of cancer cells in untreated conditions or after the treatment with doxorubicin, which causes a block of G2-phase of the cell cycle." (PMID 32397616, 2020). "Our observations might open novel therapeutic strategies to promote cancer cell death by targeting the TFEB-p21 pathway in the presence of genotoxic agents." (PMID 32397616, 2020). "TFEB overexpression is related to the progression of cancers." (PMID 33292395, 2020). "The discrepancy regarding TFEB in cancer suggests that TFEB may fulfill context-specific roles in distinct cell types." (PMID 30979895, 2019). "Using datasets available at the cancer genome atlas (TCGA), we found that the gene encoding the endolysosomal cation channel, TRPML1 (MCOLN1), was upregulated in oncogenic HRAS-expressing tumors due to the combined actions of MiTF and TFEB." (PMID 31526156, 2019). "We have recently demonstrated that TFEB is activated following exposure of cancer cells to lysosomotropic anticancer drugs, resulting in lysosome-mediated cancer drug resistance via increased lysosomal biogenesis, lysosomal drug sequestration, and drug extrusion through lysosomal exocytosis." (PMID 30546014, 2018). "This may unveil new strategies for pharmacological intervention in conditions benefiting from induction or inhibition of TFEB activity, such as neurodegenerative disorders and cancer, respectively." (PMID 30120233, 2018). "So far, we recognize that the TFEB and other MiT/TFE members, associated with autophagic or lysosomal dysfunction and the accumulation of toxic aggregates, present more and more close connection with cancers." (PMID 29903018, 2018). "Thus, cancer cells activate TFEB in response to nutrient deprivation to regulate autophagy, which then degrades unnecessary cellular organelles and macromolecules to provide nutrients." (PMID 27892481, 2016). "In non–small cell lung carcinomas, TFEB expression is associated with poor cancer prognosis, although the mechanism is not clear." (PMID 27992857, 2016). "Here, we show the generation and characterization of two different transgenic mouse lines that overexpress TFEB specifically in the kidney in a constitutive and inducible manner, respectively, which recapitulate both the cystic changes and the cancer phenotype of the human pathology." (PMID 27668431, 2016). "Tumor suppressors PRF1 and BRCA1, as well as oncogene TFEB, all of which may play an important role in cancer cell survival during the progress of metastasis, were predicted as driver genes only in metastases." (PMID 24405831, 2014).
cancer (continued). "Cancer cells need free AAs because of their highly anabolic state; for this reason, the autophagy–lysosome circuit is upregulated in cancer cells, and Transcription Factor EB (TFEB), a master regulator of the autophagy–lysosome pathway, sustains AA pools via protein breakdown." (PMID 41008653, 2025). "Furthermore, clinical data support the beneficial role of TFEB in cancer treatment." (PMID 40083935, 2025). "Notably, TFEB’s vital role is conserved in mouse embryonic and human cancer diapause." (PMID 40588651, 2025). "In addition to the kidneys, elevated TFEB expression promotes cancer development in other organs." (PMID 38365838, 2024). "Consequently, the elevation in autophagic flux observed in drug-resistant cancer cells might result from either an increased availability of TFEB itself or from its increased transcriptional activity." (PMID 38203629, 2023). "Besides its role in cellular metabolism, TFEB is a crucial player in cancer biology." (PMID 36888606, 2023). "Furthermore, TFEB acts as a transcription factor for several proteins that are essential for autophagy, which is a complex process promoting cell survival during stress conditions and a driving factor for the chemoresistance of cancer cells." (PMID 34344390, 2021). "RNA-based therapeutics are expected to soar after the success of RNA-based vaccines; in this sense, numerous studies indicate TFEB is an effective target for the modulation of autophagy and lysosomal activity to successfully counteract different pathological conditions, including cancer." (PMID 34685734, 2021). "In general, TFEB may play dual roles in different cancers, depending on the context and niche." (PMID 33803301, 2021). "Thus, TFEB activation can promote G1 arrest through p21 upregulation, delaying G2/M phase arrest, and increasing cell survival upon chemotherapeutic treatment of cancer cells." (PMID 32397616, 2020). "Moreover, TFEB was shown to regulate quiescent states, and several tumors rely on low-growing and stem-like cells to survive cancer treatments." (PMID 33490073, 2020). "Importantly, under stress full conditions such as chemotherapy treatment, an intricate interplay between the homeostatic TFEB and autophagy pathways may occur in cancer cells that will ultimately dictate their fate between cell death or survival." (PMID 31413743, 2019). "Indeed, among these targets, transcription of MAP1LC3B and ATG14 genes are directly controlled by this CARM1/TFEB during starvation, a process that could be also involved in cancers when cancer cells are frequently deprived." (PMID 31861179, 2019). "We hypothesize that upregulation of TFEB, PGC1α and PPARα as well as increasing lipid uptake via CD36 as discovered in our study is an escape mechanism, by which the cancer cells try to compensate for defective mitochondria and loss of energy induced by V-ATPase inhibition." (PMID 31358011, 2019). "Therefore, inhibition of TFEB could prevent metabolic adaptation of cancer cells to energy starvation, and thus represents a promising strategy for the treatment of cancers harboring KRAS mutations." (PMID 30400219, 2018). "Thus, LD-induced inhibition of mTORC1 might have therapeutic implications by inhibiting cancer cell growth, apart from the activation of TFEB and the consequent increase in lysosomal biogenesis, lysosomal exocytosis, and autophagy." (PMID 30546014, 2018). "In addition, nuclear TFEB translocation may re-establish autophagy, enforcing metabolic activity in cancer cells normally seen in periods of starvation conducted by the autophagy program." (PMID 26654961, 2015).
cancer (continued). "For example, in macrophages and cancer cells, S6K1 enhances lysosomal biogenesis and autophagic capacity by supporting transcription factor EB (TFEB) activation and modulating the translation of key autophagy regulators." (PMID 40649702, 2025). "The results uncover a hierarchical cascade whereby microenvironmental stresses, including glucose limitation, lead MITF, TFEB, and TFE3 to drive distinct biologically important transcription programs that underpin phenotypic transitions in cancer." (PMID 41275493, 2025). "In cancer, lactylation promotes the transcriptional activities of YAP while TFEB lactylation at K91 prevents its proteasome degradation, resulting in high levels of autophagy." (PMID 40651947, 2025). "Interestingly, RNA sequencing (RNA-seq) revealed an upregulation in the levels of TFEB mRNA during diapause, and gene-set enrichment analysis revealed altered TGFβ signaling, further supporting the similarity of diapause-like states in human cancer cells and worms." (PMID 40588651, 2025). "This revealed that cancer‐derived iPSCs exhibited high levels of MYC and the histone deacetylase 2 (HDAC2), but decreased levels of TFEB, compared to the parental fibroblasts." (PMID 41097905, 2025). "We previously reported that CC promotes nuclear translocation of TFEB and increases autophagy and lysosomal biogenesis in HeLa and MDA-MB-231 cancer cells." (PMID 39454957, 2024). "The levels of these lipid ligands change during cancer, which can directly influence PPAR and TFEB activation and, thereby, autophagy during cancer." (PMID 37190124, 2023). "In cancer cells, suberoylanilide hydroxamic acid (SAHA), a well‐established HDAC inhibitor, promotes acetylation of TFEB at K91, K103, K116, and K430 by enhancing the interaction of acetyl‐coenzyme A acetyltransferase 1 (ACAT1) with TFEB." (PMID 36184826, 2023). "Either the overexpression and/or constitutive nuclear localization of TFEB and TFE3 promote the growth of various types of cancer." (PMID 35406743, 2022). "However, whether TRPML1 is involved in the TFEB-dependent cancer development remains unclear." (PMID 33419007, 2021). "We first analyzed the correlation between TFEB expression and half maximal inhibitory concentration (IC50) of CDDP using Genomics of Drug Sensitivity in Cancer (GDSC) data." (PMID 34091590, 2021). "All these results highlight an important role of mTORC1/TFEB/TFE3 feedback loop in cancer biology and encourage to better-characterize how mTORC1-FLCN/FNIP-AMPK interplay to regulate TFEB/TFE3 activity." (PMID 33981707, 2021). "In these tumors, cancer cells expressing high levels of c-MYC and HDAC2 in the nucleus force relocation of TFEB/TFE3 to the cytoplasm, which inhibits lysosomal biogenesis and autophagy." (PMID 33718382, 2021). "In our study, when lysosomal functions were inhibited either by TFEB or ATP6V0E2 knockdown, anlotinib treatment increased cancer cell death." (PMID 32839434, 2020). "TFEB or ATP6V0E2 knockdown attenuates anlotinib-induced lysosomal activation, which further enhances the cytotoxicity of anlotinib and leads to more cancer cell apoptosis." (PMID 32839434, 2020). "The currently confirmed direct anti-cancer targets of ginkgetin are VEGF, p62 and TFEB." (PMID 40762894, 2025). "Given that both TFEB and UPR enhance cancer stemness and are responsive to metabolic stress, we hypothesized that TFEB modulates 2-DG–induced UPR." (PMID 39814550, 2025). "The identification of TFEB as the master regulator of lysosomal activity, and the fact that TFEB and other members of the MiT/TFE family are considered oncogenes in several cancers, have highlighted the importance of lysosomes in cancer and underscored its potential as a therapeutic target." (PMID 38474423, 2024). "Together, our findings reveal an unexpected function of TFEB in regulating EMT, which might provide insights into injured heart repair and control of cancer progression." (PMID 36057632, 2022).